SNORA70 (small nucleolar RNA, H/ACA box 70)
Synonyms: U70; DXS648E; RNU70
Gene: Small nucleolar RNA gene on chromosome X (154,400,281 to 154,400,415, forward strand). Ensembl gene ENSG00000207165.
Gene Ontology:
Biological process: RNA processing
Cellular component: nucleolus
Homologues: Orthologues: chimpanzee SNORA70 (99% identical), macaque SNORA70 (95% identical). Paralogues in human: SNORA70I (94% identical), SNORA70H (93% identical), SNORA70G (92% identical), SNORA70J (92% identical), SNORA70B (90% identical), SNORA70C (90% identical), SNORA70 (90% identical), SNORA70D (89% identical), SNORA70 (88% identical), SNORA70 (87% identical), SNORA70E (87% identical), SNORA70 (85% identical), and 16 more.
Diseases named in the same sentence as SNORA70 in open-access papers:
SNORA70 is named in the same sentence as 1 disease in open-access papers, as found by Europe PMC text mining. Sharing a sentence is not in itself a finding about the gene and the disease.
SNORA70 shares sentences with these, for which no sentence is quoted: infection (1 paper).